INS (insulin)
Diseases named in the same sentence as INS in open-access papers (continued):
Sharing a sentence is not in itself a finding about the gene and the disease.
tumor (continued). "Some of these molecular alterations found in squamous PDAC, such as inhibition of pancreatic epithelial differentiation genes (HNF4A and GATA6) together with increased hypoxia, HIF1A, C-MYC and WNT, insulin, and PI3K-AKT signaling, promote a metabolic rewiring of tumor cells to glycolysis." (PMID 34503261, 2021). "Nevertheless, our observations suggest that Wg-mediated up-regulation of insulin/IGF signaling might be important for restraining both Foxo and Atg1 activities in yki3S/A tumors, which is critical for supporting tumor growth." (PMID 34078667, 2021). "Although insulin does not have mitogenic properties, its excessive increase can be a signal for tumor growth and its aggressiveness, including CRC." (PMID 34208601, 2021). "A total of nine pancreatic tumor sections were histologically examined; six were insulin-positive tumors and three were insulin-negative tumors, with mean tumor sizes of 1.3 ± 0.3 and 2.0 ± 0.6 mm in diameter, respectively." (PMID 34294854, 2021). "Insulin inhibits the production of IGF-1-binding proteins from the liver, which leads to an increased concentration of biologically active free IGF-1, which is involved in tumor promotion." (PMID 34638244, 2021). "Moreover, epigenetic reprogramming of PANC-1 cells with 5′-Aza did not only increase NGN3, INS, and SST expression but also induced a less aggressive phenotype with impaired tumor growth and improved response to the cytotoxic drug gemcitabine." (PMID 34771704, 2021). "The results showed that although AdipoRon at the given dose effectively ameliorated the prediabetic condition in terms of reductions in blood glucose and insulin, the treatment failed to suppress tumour growth." (PMID 33536560, 2021). "Adiponectin mediates its insulin-sensitizing effect through activation of AMP-activated protein kinase (AMPK) and peroxisome proliferator-activated receptor–alpha pathways with resultant suppression of tumor growth in animal models." (PMID 34485815, 2021). "Notably, miR‐7 can act as a tumor suppressor to induce growth factor signal transduction; therefore, we conclude that circ‐CDR1as may regulate the stability of the target gene miR‐7 through the sponge action of miRNAs, regulating insulin secretion and tumorigenesis." (PMID 34796685, 2021). "Although the lifespan-extending effects of protein restriction are not fully understood, effects on insulin signaling and TOR signaling might not only explain these effects, but also the beneficial effects on tumor growth." (PMID 34766923, 2021). "In accordance with previous retrospective studies 39,58, we demonstrated that insulin treatment of T2DM patients did not influence the distribution of 18F-FDG uptake in NSCLC tumor lesions." (PMID 33391452, 2021). "Given that GLUT4 is an insulin‐responsive glucose transporter, the increased GLUT4 level seen in our tumour model could be either because of the direct effect of SIRT6 on Glut4 promoter or a consequence of increased plasma insulin levels or both." (PMID 34212132, 2021). "While normal adrenal tissue showed no detectable expression of INS transcripts, 17 of the 20 tumours had detectable expression." (PMID 34170845, 2021). "TNF-α is produced by activated monocytes/macrophages, that promote cell proliferation and differentiation and also synergize with epi-epidermal growth factor and insulin to promote the expression of the EGF receptor and produce growth factor-like effects on some tumor cells." (PMID 33494759, 2021). "The main mechanism involves insulin and insulin growth factor (IGF), which stimulate tumor growth." (PMID 33549043, 2021). "There are also reports of patients with hyperinsulinemic hypoglycaemia without convincing evidence that their extrapancreatic tumour produced the insulin." (PMID 34170845, 2021).
tumor (continued). "Studies using a β-3 adrenergic receptor agonist to reduce circulating insulin levels or using a tyrosine kinase inhibitor that inhibited both the IR and IGF-1R reported reduced the tumor growth in MKR mice, further supporting our in vivo observation with DZ71–73." (PMID 33495474, 2021). "Therefore, this pathway can bypass the downstream signals in the insulin pathway, such as PTEN and AKT, to regulate cellular metabolism, which is a typical feature of tumor cells." (PMID 33375360, 2020). "Insulin, as it was described in the previous section, promotes the synthesis and activity of IGF-1 as well as mitosis and cell proliferation and thus, it exerts tumour growth-stimulating effects." (PMID 33008076, 2020). "The increased insulin sensitivity in tumoral area could promote tumor growth in an independent Wnt signaling pathway (under dependent-insulin pathway), since SFRP2 is considered an adipokines that promotes insulin sensitivity and insulin resistance." (PMID 32517740, 2020). "While the drug normalizes glucose tolerance and significantly reduces circulating insulin, it did not decrease tumor liver metastasis of FF mice." (PMID 32879136, 2020). "Although we observed time-based effects during tumor monitoring (21st vs. 28th day, p < 0.05), we did not observe differences in glucose and insulin levels across different protocols (DOX or DOX + EXER)." (PMID 33233839, 2020). "As in the case of insulin and IR, the expression of the ligand (IGF1) and its receptor (IGF1R) within the same tumor could provide proof of an autocrine-paracrine signaling loop of RCC cells stimulation." (PMID 30929166, 2019). "The tumor was positive for CK+(CKLow), CgA(+), CD56(+), Syn(+), insulin(+), and β-catenin(+)." (PMID 32009878, 2019). "Glucose is an essential fuel for embryo and tumor cells wherein glucose uptake is independent of insulin." (PMID 31019893, 2019). "Insulin stimulates the synthesis of IGF-1 and leads to tumor growth." (PMID 30636976, 2019). "When the animals were treated or pretreated with insulin (groups 4 and 5, respectively) combined with FU, no raise in the tumor weight was observed." (PMID 31719636, 2019). "Immunohistochemically, the largest tumor was negative for insulin, but some smaller tumors showed insulin-positive neuroendocrine cells dispersed (less than 70%) in the lesions." (PMID 30795813, 2019). "Addition of insulin to primary tumor derived RCC cell lines (Caki-2, 769-P, 786-O) did not affect it viability or proliferation in first 72 h after stimulation." (PMID 30929166, 2019). "The normoxic stabilization of HIF1α at the protein level was found in various tumor cell lines after the application of several growth factors (e.g., EGF or insulin) or fetal bovine serum only in the presence of the amino acid glutamine and as a result of glutaminolysis." (PMID 31554283, 2019). "DEPTOR significantly promotes the growth of tumor cells in vivo and in vitro by inhibiting mTOR, which releases the negative feedback on the insulin PI3K/AKT pathway and therefore promotes cell survival and prevents apoptosis." (PMID 31228948, 2019). "Similar to RT2_DKO mice, metastases were also insulin-negative, suggesting migration of dedifferentiated tumor cells." (PMID 30405106, 2018). "Tumor-bearing trained rats also showed reduced blood glucose after insulin injection compared to counterparts without tumors at the same collection times (p = 0.001)." (PMID 29867528, 2018). "Tumors of late-stage RT2_DKO mice were also often insulin-negative, providing an explanation for longer survival despite increased tumor burden." (PMID 30405106, 2018). "Tumor cell inoculation did not change the glucose-induced insulin secretion from islets isolated from Walker 256 tumor-bearing rats compared to rats without tumors." (PMID 29867528, 2018).
tumor (continued). "RNAi knockdown of ImpL2 in the tumour was sufficient to reduce the systemic insulin resistant phenotype and thus partially rescue the wasting phenotypes observed in peripheral tissues, without impacting the growth of the tumour." (PMID 29725601, 2018). "Tumor-bearing trained rats showed a reduction in insulin levels compared to their counterparts without tumors (p < 0.01)." (PMID 29867528, 2018). "In the present study, we also showed that low glucose and insulin levels before tumor cell inoculation did not revert even 15 days after the last training session." (PMID 29867528, 2018). "Frequent injections with insulin glargine, a compound that only mildly activates the IGF1R in vivo, showed a similar trend but the observed tumor latency time decrease was not significant compared to regular insulin." (PMID 28173837, 2017). "Evidence has also suggested that IGFBPs may have insulin/IGF-independent functions, including during tumour progression." (PMID 28880250, 2017). "Frequent injections with insulin analogues that only mildly activated the IGF1R in vivo (glargine and insulin) did not significantly decrease the tumor latency time in this mouse model." (PMID 28173837, 2017). "At the beginning of the primary culture of tumour cells from the patient ascites, cells grew in RPMI 1640 culture medium supplemented with 10% patient ascites, 10% foetal bovine serum (FBS), 10 ng/mL insulin, and 10 ng/mL of transferrin at 37 °C with 5% CO2." (PMID 28860565, 2017). "The understanding of this network might contribute to finding a way to contradict the biological feedback between glycans and insulin/IGF system, and consequently to control tumour development and progression." (PMID 28880250, 2017). "Since mice were chronically exposed to insulin analogues that activate (to a lesser or greater extent) the IGF1R, we postulated that the decreased tumor latency time (after X10/IGF1 stimulation) would be a direct result of an upregulated IGF1R signaling pathway." (PMID 28173837, 2017). "Yet, insulin glargine and normal insulin, did not significantly decrease the latency time for (mammary gland) tumor development." (PMID 25848982, 2015). "While ketones are increased and insulin is decreased, these changes in energy substrates and signaling molecules did not influence tumor growth." (PMID 26192445, 2015). "Here we report a previously unrecognized tumour-promoting mechanism for stress protein TRB3, which mediates a reciprocal antagonism between autophagic and proteasomal degradation systems and connects insulin/IGF to malignant promotion." (PMID 26268733, 2015). "From the in vivo studies it can be concluded that human insulin is not carcinogenic as the number of tumours that developed in the human-insulin-treated group was similar to the vehicle-injected group." (PMID 26242987, 2015). "The remaining candidate biomarkers include gene signatures indicative of elevated tumor insulin/IGF system activity, signaling molecules connected to the insulin/IGF axis that may mediate drug resistance, and other markers signifying drug response." (PMID 26029167, 2015). "The potential mechanism could be through insulin growth factor-1 (IGF-1), where increasing energy could be responsible for glycemic overload and a compensatory increase of serum insulin and related IGF-1, a promoter of tumor cell growth in vitro." (PMID 25763533, 2015). "In our study, restoration of wildtype Grb10 expression in Nf1 mutant tumor cells lacking Grb10 expression failed to suppress phosphorylation of S6Kinase upon exposure to insulin." (PMID 26000738, 2015). "TRB3 expression in tumour nodules from TRB3 knockdown KK-Ay mice was much lower than that from control KK-Ay mice, suggesting that the higher insulin/IGF-1 in TRB3 knockdown KK-Ay mice cannot enhance TRB3 expression in the inoculated tumour cells as it does in the control KK-Ay mice." (PMID 26268733, 2015).
tumor (continued). "Here we identify TRB3 acting as a link between insulin/IGF and tumour development and progression." (PMID 26268733, 2015). "Here, the authors show a tumour promoting mechanism for stress protein TRB3 which mediates a reciprocal antagonism between autophagic and proteasomal degradation systems and connects insulin/IGF to malignant promotion." (PMID 26268733, 2015). "In addition to restricting glucose as fuel for tumors, the tumor suppressive effect of the ketogenic diet appears to be mediated through reduction of serum IGF-I and insulin levels via GH resistance." (PMID 26029167, 2015). "In this setting, a proper and orderly diagnostic approach is essential to rule out the presence of an insulin-secreting tumor." (PMID 25816027, 2015). "Some tumours produce their own autocrine IGF1 (not insulin), most notably myeloma, but the majority of tumours do not, and thus are likely to depend on systemic levels for their growth." (PMID 26284118, 2015). "The limitations of this study include its retrospective nature and the lack of tumor biology data such as gene mutation and expression as well as laboratory data regarding serum IGF1, insulin, and adipocyte-derived leptin levels." (PMID 26684001, 2015). "Since a low carbohydrate diet can decrease blood insulin level, we hypothesized that the diet may inhibit the PI3K pathway to slow down tumor growth." (PMID 26192445, 2015). "All in all, based on the current tumor model, the data suggest that glargine users are not facing an increased carcinogenic hazard compared to insulin NPH users." (PMID 25848982, 2015). "Our results reveal that S phase progression of tumor GSCs, like that of normal GSCs, is delayed by aging and is independent of regulation by insulin signaling." (PMID 25470527, 2015). "Since both insulin and IGF-1 have been reported to fuel some tumours, having more or less BAT may affect the overall systemic insulin sensitivity and thereby have an indirect influence of tumour progression." (PMID 26523094, 2015). "In humans, insulin may enhance tumor progression via the INSR, while insulin analogs with INSR dissociation rates slower than insulin may have greater mitogenic activity." (PMID 24533136, 2014). "Further review of immunohistochemistry from the original tumour sample showed it to be negative for insulin, glucagon, PPP and somatostatin." (PMID 24683485, 2014). "In an earlier study, we demonstrated that metformin, independent of improving insulin sensitivity, was effective in controlling tumor development in obese rats." (PMID 24858012, 2014). "Insulin binds dominantly to tumor cells rather than to fat and fibrous tissue within tumors as demonstrated by autoradiographic studies." (PMID 24885964, 2014). "Tumours secreting insulin are usually of pancreatic origin; however, this was not visualised on cross-sectional imaging or nuclear medicine scanning." (PMID 24683485, 2014). "The absence of insulin and other growth factors in this condition and the similarity to the environmental condition of fibroblasts surrounding tumor cells and ulcer, made us to investigate anaerobic glycolysis in these cells." (PMID 25035856, 2014). "We did not observe differences in plasma insulin levels between the mouse cohorts, suggesting that the observed signaling effects were due to a direct interaction of the drugs with tumor cells." (PMID 25361177, 2014). "Furthermore, metformin appears to exert an insulin-independent suppressive effect on CYP17-lyase and androstenedione production by human ovarian theca-like tumour cells." (PMID 25139174, 2014). "Very few cases of insulin and ACTH co-secretion by a single tumour have been described." (PMID 24683485, 2014). "Absence of insulin and other growth factors in serum deprivation condition and similarity of this condition to the environment of tumor cells and ulcer made us to investigate anaerobic glycolysis in these cells." (PMID 25035856, 2014).
tumor (continued). "The insulin induced-up- regulation of PKM2, with evident increase at as low as 1 nM insulin, is an important observation, since PKM2 has been reported essential for aerobic glycolysis and tumor growth." (PMID 23837608, 2013). "Interestingly, our results further showed that activation of insulin and IGF-I signaling, through growth factor stimulation, significantly enhanced (P<0.01) tumor cell invasion of MDA-MB-435+Ecad." (PMID 24282611, 2013). "The TNM tumor stage at diagnosis was not higher among patients on glargine compared to patients on other types of insulin (T1/T2 85% vs. 68%, T3/T4 15% vs. 32%, p = 0.32; N1 54% vs. 58%, p = 0.80; M1 8% vs. 6%, respectively)." (PMID 24131755, 2013). "The evolutionarily conserved nature of our results, and the established role the APC plays in tumor development and progression, suggests that the APC may be a potential downstream target of the insulin signaling pathway." (PMID 22438832, 2012). "Many tumour types have upregulated expression of IGF-1R, INSR, and potentially hybrid INSR/IGF-1Rs which facilitate increased activation of mitogenic, prosurvival and protein synthesis pathways with the increased levels of ligands insulin, IGF-1, or IGF-2." (PMID 22548055, 2012). "In this situation, the continuous activity of insulin in non-resistant tissues promotes the activation of the mTORC1 system, thereby favoring cellular proliferation and tumor development." (PMID 23226562, 2012). "Tumor apoptosis showed a strong negative correlation with circulating insulin (r=−0.74, P<0.01) and serum visfatin concentrations (r=−0.53, P=0.02), but not with glucose concentration (r=−0.16, P=0.25)." (PMID 23170114, 2012). "Notably, only 3 out of 11 mice in the 15% CHO group died with having a tumor compared to 7 out of 10 in the 55% CHO group; at death, significantly lower plasma insulin levels had been measured for the low CHO group." (PMID 22029671, 2011). "Furthermore, the ligand of insulin and insulin-like receptors, IGF-2, was strongly upregulated in tumor cells, whereas there were moderate changes in transgenic cells (not detected by differential expression analysis)." (PMID 21464922, 2011). "Given the well documented role of heparanase in tumor metastasis and angiogenesis, it is plausible that insulin, with or without glucose, stimulates secretion of active heparanase by tumor cells, thus accelerating tumor progression." (PMID 21364956, 2011). "Studies using diabetic non-obese mice demonstrated the link betweendiabetes and tumor development and metastasis, which is dependent on insulin and insulingrowth factor-1 (IGF-1)." (PMID 23908801, 2011). "No tumors predominantly expressed insulin, pancreatic polypeptide, or somatostatin, although some harbored focal aggregates of tumor cells expressing one of those hormones." (PMID 21853126, 2011). "It was shown that almost half of the genes that affect tumor growth also affect the lifespan of animals that do not have tumors, indicating that the ability of the insulin/IGF-1 pathway to couple longevity and tumor resistance extends downstream of DAF-16." (PMID 21084729, 2010). "Post-prandial insulin at 10 wk was elevated in both groups, although host metabolism was likely confounded by tumor pathology, and this change does not necessarily diminish the early effect of post-prandial insulin on tumor promotion." (PMID 20148110, 2010). "The downstream targets of the insulin-regulated cascade that couples GSC proliferation with nutritional status are therefore of great interest, potentially representing novel mediators of PTEN signaling that contribute to its tumor suppressive properties." (PMID 17150096, 2006). "Weight loss associated with the MAC16 tumour was significantly reduced both by a ketogenic diet (80% MCT) and by daily insulin injections without an increase in either food or water consumption." (PMID 2736199, 1989).